SPATA8 (spermatogenesis associated 8)
Synonyms: MGC44294; SRG8
Gene: Long non-coding RNA gene on chromosome 15 (96,780,975 to 96,785,617, forward strand). Ensembl gene ENSG00000185594.
Diseases named in the same sentence as SPATA8 in open-access papers:
SPATA8 is named in the same sentence as 1 disease in open-access papers, as found by Europe PMC text mining. Sharing a sentence is not in itself a finding about the gene and the disease. The quoted sentences say what the papers report.
melanoma (1 paper, 2014). A malignant, usually aggressive tumor composed of atypical, neoplastic melanocytes. "However SPATA8 mutation c.52G >A (p.Glu18Lys) is known to be linked with melanoma indicating its potential role in this disease." (PMID 25437182, 2014).